LPXN (leupaxin)
Diseases named in the same sentence as LPXN in open-access papers:
LPXN is named in the same sentence as 36 diseases in open-access papers, as found by Europe PMC text mining. Sharing a sentence is not in itself a finding about the gene and the disease. The quoted sentences say what the papers report.
prostate carcinoma (6 papers, 2012 to 2026). A carcinoma that arises from epithelial cells of the prostate gland. "Depletion of LPXN expression reduces prostate cell migration and invasion, while its overexpression promotes prostate cancer progression." (PMID 38283944, 2023). "Recently, we demonstrated elevated expression levels of LPXN in approximately 20% of prostate cancer patients and showed that knockdown of LPXN by RNAi reduces migration and invasion of PC-3 and DU 145 PCa cell lines." (PMID 26079947, 2015). "Originally identified in hematopoietic cells, leupaxin was found to be expressed in a series of other tissues, e.g., smooth muscle cells and prostate cancer cells." (PMID 25955236, 2015). "Leupaxin belongs to the group of paxillin proteins and was reported to play a major role in the invasion and migration of prostate cancer cells." (PMID 25955236, 2015). "Recently, it was shown that leupaxin expression in human prostate cancer correlates with tumour stage and that leupaxin downregulation in prostate cancer cells results in decreased migratory ability and invasiveness." (PMID 25955236, 2015). "The focal adhesion protein leupaxin (LPXN) is overexpressed in a subset of prostate cancers (PCa) and is involved in the progression of PCa." (PMID 26079947, 2015). "As it was shown that leupaxin interacts and activates the androgen receptor in prostate cancer cells, a putative interaction between leupaxin and the ERs α and β in breast cancer cells was investigated using direct yeast-two-hybrid experiments." (PMID 25955236, 2015). "Recently, we found that LPXN was overexpressed in approximately 20% of prostate cancer patients and that LPXN expression correlated with the differentiation stage of these tumors." (PMID 26079947, 2015). "It is noteworthy that upregulation of leupaxin expression was detectable in three out of four prostate cancer tissues confirming previous results of our group." (PMID 25955236, 2015). "From prostate cancer cells it is known that the leupaxin-LD4 motif is most important for nuclear export of leupaxin." (PMID 25955236, 2015). "Prostate cancer cells expressed LPXN, which regulated invasion and adhesion." (PMID 39867879, 2024). "This fact is also supported by previous studies from our group: we could demonstrate a correlation of LPXN expression with the Gleason score of human prostate carcinomas." (PMID 26079947, 2015). "In vitro studies also suggest that the migration of prostate cancer cells (PC-3) may be regulated by protein complexes involving leupaxin, Pyk2, and the tyrosine phosphatase PTP-PEST, which dephosphorylates Pyk2." (PMID 22888421, 2012). "Thus, the LPXN interaction with CaD might regulate actin-cytoskeletal remodeling during prostate cancer progression." (PMID 26079947, 2015). "Elevated levels of Leupaxin (LPXN) have been correlated with the evolution and progression of certain malignant tumors, such as prostate cancer, colon cancer, breast cancer, and osteosarcoma." (PMID 41262528, 2026). "It was also demonstrated that leupaxin forms a signaling complex with Pyk2, c-Src, and PTP-PEST which regulates the migration of prostate cancer cells." (PMID 22888421, 2012).
bladder cancer (5 papers, 2020 to 2024). "Through the PI3K/AKT pathway, LPXN also stimulate the proliferation, metastasis, and angiogenesis of bladder cancer." (PMID 39867879, 2024). "Leupaxin (LPXN) is vital in tumourigenesis and the progression of bladder cancer by upregulating the expression of S100P via the PI3K/AKT pathway." (PMID 34439758, 2021). "Leupaxin promotes bladder cancer proliferation, metastasis, and angiogenesis through the PI3K/AKT pathway." (PMID 32239176, 2020). "In addition, some studies have shown that LPXN is also expressed in prostate cells, bladder cancer cells, and smooth muscle cells." (PMID 38159847, 2023). "Leupaxin promotes proliferation, angiogenesis and metastasis through the PI3K-Akt signaling pathway, then becomes a potential therapeutic target in bladder cancer." (PMID 38370370, 2024).
breast carcinoma (3 papers, 2015 to 2026). "Taken together, our results underline the role of leupaxin as an important factor in the progression of breast cancers and give a further basis to investigate the potential of leupaxin as a target for the development of novel therapeutic strategies." (PMID 25955236, 2015). "Supported by the results of the in vitro studies we postulate leupaxin to be an important player during breast cancer progression." (PMID 25955236, 2015). "Leupaxin localizes in these mammary carcinoma cells at focal adhesion sites and shuttles between membrane and nucleus via its LD4 motif as major nuclear export signal." (PMID 25955236, 2015). "We obtained the first hints of an involvement of leupaxin in breast cancer from an array study containing patient matched tumour and normal tissues of a variety of cancer types." (PMID 25955236, 2015). "In conclusion, we showed in the present study that leupaxin is overexpressed in human breast cancers." (PMID 25955236, 2015). "Mutation of important amino acids within this motif led to the accumulation of leupaxin in the nucleus in MDA-MB-231 cells demonstrating that leupaxin also shuttles between cytoplasm and nucleus in breast cancer cells." (PMID 25955236, 2015). "To further explore the involvement of leupaxin in breast cancer we knocked down leupaxin expression using previously established siRNAs." (PMID 25955236, 2015). "Further analysis of leupaxin expression in 127 breast cancer specimens showed expression of leupaxin in 49, 40 and 22% of DCIS, DC and LC, respectively." (PMID 25955236, 2015). "However, more pronounced staining of leupaxin was observed mainly in DCs, which represents the more advanced breast cancer stage." (PMID 25955236, 2015). "The expression of leupaxin was evaluated in seven established breast cancer cell lines." (PMID 25955236, 2015). "Collectively, these results show that leupaxin has particular influence on the progression and invasion of breast cancer cells and may therefore represent an interesting candidate protein for diagnosis and therapeutic interventions." (PMID 25955236, 2015). "Downregulation of leupaxin expression in breast cancer cells decreases migration and invasion." (PMID 25955236, 2015). "In addition, immunohistochemical studies using a leupaxin-specific antibody on human breast cancer specimens (n=127) revealed that leupaxin is expressed mainly in invasive ductal carcinomas and ductal carcinoma in situ (40 and 49% respectively), and only in a minority of lobular mammary carcinomas." (PMID 25955236, 2015). "Therefore, leupaxin and its involved genes and pathways could serve as potential targets in the development of new therapeutic strategies for breast cancer." (PMID 25955236, 2015). "Expression analyses for leupaxin in metastases of breast cancers may strengthen this hypothesis." (PMID 25955236, 2015). "To further evaluate if leupaxin plays an important role also during breast cancer progression we used HCC70 and MDA-MB-231 showing highest leupaxin expression for further analyses." (PMID 25955236, 2015). "The focal adhesion protein leupaxin (LPXN) is a transcriptional coactivator and has been shown to promote cell migration, adhesion and invasion in different entities, such as prostate or breast cancer." (PMID 36056084, 2022). "All other cell lines derived from breast cancer metastases showed low or even no expression of leupaxin." (PMID 25955236, 2015). "In the present study, we provide evidence that the focal adhesion protein leupaxin is involved in the regulation of ER action as a co-factor and that it is expressed in breast cancers, but not in normal breast epithelial cells." (PMID 25955236, 2015).
colon cancer (2 papers, 2015 to 2026). "Other cancer types showed an equal distribution of patients with up or downregulated leupaxin expression, e.g., ovarian and colon cancer, and were therefore considered to be not relevant in this study." (PMID 25955236, 2015).
Obesity (2 papers, 2023 to 2025). Accumulation of substantial excess body fat. "In contrast, among the genes interacting with key adipogenic factors, LPXN, TNC, THBS1, and OGG1 have been directly associated with obesity and fat accumulation." (PMID 40130165, 2025). "So we analyzed expression changes of Hic-5 and LPXN in the diet-induced obesity model." (PMID 38159847, 2023). "Hic-5 and LPXN can promote the accumulation of CIDEC, enable adipocytes to store more lipids, and may avoid more fat ectopic storage, thereby alleviating fatty liver and other metabolic diseases caused by obesity." (PMID 38159847, 2023). "The data showed that both the expression levels of Hic-5 and LPXN were upregulated in white adipose tissues of diet-induced obesity mice, implying that Hic-5 and LPXN may promote the stability of CIDEC by regulating its ubiquitination or deubiquitination during the development of obesity." (PMID 38159847, 2023).
acute leukemia (1 paper, 2013). A clonal (malignant) hematopoietic disorder with an acute onset, affecting the bone marrow and the peripheral blood. "LPXN was found to be a member of a fusion protein with RUNX1 in human acute leukemia where wild-type LPXN was shown to transform NIH 3T3 cells." (PMID 23349640, 2013).
acute monocytic leukemia (1 paper, 2022). Acute monoblastic leukemia (AML-M5), is one of the most common subtypes of acute myeloid leukemia (AML) that is either comprised of more than 80% of monoblasts (AML-M5a) or 30-80% monoblasts with (pro)monocytic differentiation (AML-M5b). "Depletion of LPXN in an acute monocytic leukemia cell line (SHI-1) was associated with decreased malignant proliferation and transmembrane invasion." (PMID 36056084, 2022).
amyloidosis (1 paper, 2025). A disorder characterized by the localized or diffuse accumulation of amyloid protein in various anatomic sites. "In the SMC-calc vs. SMC comparison based on limma, clusters related to high-density lipoprotein (HDL) assembly (PF4V1, APOA1, LPXN, AFP, A2M, and MMP1) and amyloidosis (CX3CL1, APOE, PLIN3, TGFBI, and CH25H) were identified." (PMID 41301179, 2025).
Cirrhosis (1 paper, 2024). A chronic disorder of the liver in which liver tissue becomes scarred and is partially replaced by regenerative nodules and fibrotic tissue resulting in loss of liver function. "Considering that COL1A2 is a collagen, we performed a correlation analysis between SOX4, LGALS3, SERPINE2, CD52, LPXN, and MPP6 and the progression of cirrhosis." (PMID 39194690, 2024).
ductal carcinoma in situ (1 paper, 2015). "49% of ductal carcinoma in situ and 40% of invasive ductal carcinomas displayed leupaxin expression." (PMID 25955236, 2015).
endometrial cancer (1 paper, 2015). Primary or metastatic malignant neoplasm involving the endometrium (mucous membrane that lines the endometrial cavity). "In the present study we were able to show by using a cDNA cancer profiling array that leupaxin is upregulated in breast and endometrial cancer, whereas downregulation of leupaxin was observed in lung cancer." (PMID 25955236, 2015).
endothelial dysfunction (1 paper, 2024). In vascular diseases, endothelial dysfunction is a systemic pathological state of the endothelium (the inner lining of blood vessels) and can be broadly defined as an imbalance between vasodilating and vasoconstricting substances produced by (or acting on) the endothelium. "This study identified key regulatory genes for endothelial dysfunction in liver fibrosis, namely SOX4, LGALS3, SERPINE2, CD52, and LPXN, which will provide new targets for the development of therapeutic strategies targeting endothelial dysfunction in LSECs and liver fibrosis." (PMID 39194690, 2024). "This study, focusing on LSECs and the molecular bases of endothelial dysfunction during liver fibrosis from different mice models, found that SOX4, LGALS3, SERPINE2, CD52, and LPXN are potential key genes associated with endothelial dysfunction in liver fibrosis." (PMID 39194690, 2024). "Therefore, SOX4, LGALS3, SERPINE2, CD52, and LPXN may serve as key regulatory genes for endothelial dysfunction in liver fibrosis LSECs." (PMID 39194690, 2024). "Moreover, we identified five key regulatory genes for endothelial dysfunction in liver fibrosis LSECs: SOX4, LGALS3, SERPINE2, CD52, and LPXN." (PMID 39194690, 2024).
esophageal squamous cell carcinoma (1 paper, 2026). Esophageal squamous cell carcinoma (ESCC) is a type of esophageal carcinoma (EC) that can affect any part of the esophagus, but is usually located in the upper or middle third. "We collected 10 pairs of clinical samples of esophageal squamous cell carcinoma from Chongqing University Cancer Hospital to verify the expression of LPXN." (PMID 41262528, 2026).
hepatocellular carcinoma (1 paper, 2021). A malignant tumor that arises from hepatocytes. "LPXN also plays a role in regulating hepatocellular carcinoma progression, at least in part, by enhancing beta-catenin transcription activity." (PMID 34439758, 2021).
liver cirrhosis (1 paper, 2024). "By analyzing the Co-DEGs associated with the progression and prognosis of liver cirrhosis, we identified five key genes: SOX4, LGALS3, SERPINE2, CD52, and LPXN." (PMID 39194690, 2024).
liver disease (1 paper, 2024). "CD52 and LPXN were moderately correlated with both liver fibrosis grade and liver disease progression, while MPP6 was weakly correlated with liver fibrosis grade and liver disease progression." (PMID 39194690, 2024).
liver fibrosis (1 paper, 2024). "Subsequently, we conducted qRT-PCR analysis to examine the expression of five key genes (SOX4, LGALS3, SERPINE2, CD52, and LPXN) in the liver tissues of mice with liver fibrosis." (PMID 39194690, 2024).
lung adenocarcinoma (1 paper, 2024). A carcinoma that arises from the lung and is characterized by the presence of malignant glandular epithelial cells. "Also the high expression of SNX20, which is connected with SASH3 and CD53 through the focal adhesion-encoding gene LPXN, has been associated with immune-active TIME and better OS in lung adenocarcinoma patients." (PMID 39107857, 2024).
lung carcinoma (1 paper, 2015). "Leupaxin was found to be overexpressed in >50% of tumours in the breast and uterus, whereas in lung cancer 71% of tumours showed downregulation of leupaxin expression." (PMID 25955236, 2015).
melanoma (1 paper, 2019). A malignant, usually aggressive tumor composed of atypical, neoplastic melanocytes. "GPX1 and LPXN have been reported to play crucial roles in multiple cancer types, including melanoma." (PMID 30779739, 2019).
metastatic melanoma (1 paper, 2008). A melanoma that has spread from its primary site to another anatomic site. "Over-expression of LPXN [GenBank:NM_004811] and NEDD9 [GenBank:NM_006403] resulted in increased migration in the bone-derived metastatic prostate cancer cell line and in promotion of metastatic melanoma, respectively." (PMID 18928525, 2008).
cancer (11 papers, 2008 to 2026). A tumor composed of atypical neoplastic, often pleomorphic cells that invade other tissues. "Together, HLF loss decreases LPXN expression, enhancing the integration of collagen stiffness and the actin cytoskeleton through paxillin, ultimately promoting cancer cell migration." (PMID 40473600, 2025). "Hic-5 and Leupaxin are highly expressed in various cancers and have been shown to promote progression and invasion of cancer cells." (PMID 40390029, 2025). "Mechanistically, HLF regulates LPXN expression, modulating the integration of collagen’s mechanical cues with the actin cytoskeleton through Paxillin, thereby suppressing cancer cell migration and lung metastasis." (PMID 40473600, 2025). "Recent studies show that LPXN is overexpressed in many cancers." (PMID 38283944, 2023). "In the present study, we further elucidated the role of leupaxin in different human cancers." (PMID 25955236, 2015). "Therefore, a cancer profiling array analysis with a human specific leupaxin probe was performed to investigate the expression profile of leupaxin in normal and matched tumour tissue samples." (PMID 25955236, 2015). "In addition, LPXN is overexpressed in several cancer cell lines." (PMID 26079947, 2015). "LPXN [GenBank:NM_004811] and NEDD9 [GenBank:NM_006403] have been reported as being involved in cancer progression." (PMID 18928525, 2008).
tumor (3 papers, 2015 to 2026). "To substantiate the relationship between LPXN expression and the therapeutic outcomes of immunotherapy in a clinical setting, we procured tumor specimens from 22 patients who received immunotherapy at the Chongqing University Cancer Hospital." (PMID 41262528, 2026). "q-PCR and immunohistochemical (IHC) staining analyses demonstrated that both LPXN and PD-L1 were upregulated in tumor samples from patients exhibiting a favorable treatment response compared to those with a poor response." (PMID 41262528, 2026).
adenocarcinoma of (1 paper, 2015). "Using the transgenic LPXN/TRAMP (transgenic adenocarcinoma of mouse prostate) mouse model with prostate-specific LPXN expression, we showed that LPXN enhances PCa progression." (PMID 26079947, 2015).
LPXN also shares sentences with these, for which no sentence is quoted: acute myeloid leukemia (1 paper); Hypercholesterolemia (1); hypertriglyceridemia (1); infection (1); invasive ductal carcinomas (1); leukemia (1); metabolic disease (1); metastatic prostate carcinoma (1); oral cancer (1); osteosarcoma (1); prostate (1); psoriasis (1).